ENSG00000124593 (novel protein)
Gene: Protein-coding gene on chromosome 6 (41,780,349 to 41,790,141, forward strand). Ensembl gene ENSG00000124593.
Genetic constraint (gnomAD): Missense variants: 526 observed, 504.98 expected, observed/expected ratio (o/e) 1.04, 90% interval 0.97 to 1.12. Synonymous variants: 208 observed, 205.25 expected, observed/expected ratio (o/e) 1.01, 90% interval 0.9 to 1.14.